ADAM8 (ADAM metallopeptidase domain 8)
Diseases named in the same sentence as ADAM8 in open-access papers (continued):
Sharing a sentence is not in itself a finding about the gene and the disease.
colon cancer (continued). "Our research suggested that ADAM8 could be a potential biomarker for the prognosis of colon cancer and induced EMT to promote the invasion of colon cancer cells via activating TGF‐β/Smad2/3 signalling pathway." (PMID 32954649, 2020). "Finally, it can be hypothesized that ADAM8 is involved not only in the malignant EMT transition of colon cancer, but also of other cancers at the doorstep of the transition." (PMID 36910158, 2023). "Moreover, we found that ADAM8 could promote the invasion of colon cancer cells and modulate EMT by TGF‐β/Smad2/3 signalling pathway." (PMID 32954649, 2020). "It was hypothesized that ADAM8 had an important effect on colon cancer EMT processes." (PMID 32954649, 2020). "In the present study, by analysing human colon cancer's data from TCGA and GTEx databases, we not only demonstrated that ADAM8 was closely related to poor prognosis in patients with colon cancer, but also found the correlation between ADAM8 and EMT‐related biomarkers." (PMID 32954649, 2020). "In addition, we found that ADAM8 could induce EMT to promote colon cancer cell invasion via activating TGF‐β/Smad2/3 signalling pathway." (PMID 32954649, 2020). "Research has demonstrated that inhibiting activities of ADAM8 and MMP can impede invasive and migratory abilities of drug-resistant colon cancer cells." (PMID 38307957, 2024). "ADAM8 has been revealed as one of three potential tumor markers, whereby the others are LYN and S100A9, for metastasis and tumor reoccurrence in colon cancers." (PMID 36910158, 2023). "To find more convincing evidence, we further verified the interaction between ADAM8 and EMT in colon cancer cells through in vitro experiments." (PMID 32954649, 2020). "In brief, these results indicated that the down‐regulation of ADAM8 attenuated EMT and colon cancer cell invasion." (PMID 32954649, 2020). "The importance and innovation of this study are to explore the correlation between ADAM8 and EMT in colon cancer cells and to highlight the pivotal role of ADAM8 in colon cancer cells’ invasion and EMT." (PMID 32954649, 2020). "The 5-year DFS in colon cancer, T3-T4 stage, N0 stage, TNM stage II, adenocarcinoma, moderate differentiation and male patient subgroups was also worse for patients with ADAM8-positive tumors than those with ADAM8-negative tumors (p < 0.05)." (PMID 25098630, 2014). "The possible mechanism might be ADAM8 activated a certain integrin, leading to the release of latent TGF‐β in colon cancer." (PMID 32954649, 2020). "The up‐regulation of ADAM8 could induce EMT phenotype and enhance the invasive ability of colon cancer cells." (PMID 32954649, 2020). "In vitro, we also proved that the up‐regulation of ADAM8 could promote EMT effect and enhance the invasive ability of colon cancer cells." (PMID 32954649, 2020). "Subgroup analysis showed that 5-year OS of colon cancer, T3-T4 stage and N0 stage was worse for patients with ADAM8-positive tumors than those with ADAM8-negative tumors (p< 0.05)." (PMID 25098630, 2014). "Further analysis for OS in each subgroup showed that patients with ADAM8 positive tumors have poorer 5-year OS than those with negative ADAM8 in colon cancer (p = 0.006), T3/T4 stage (p = 0.023) and N0 stage (p = 0.032) subgroups compared with rectal cancer, T1/T2 stage and N1-2 stage patients." (PMID 25098630, 2014). "Further analysis of survival in patient subgroups suggested that ADAM8 is a prognostic factor for colon cancer but not for rectal cancer, indicating that ADAM8 may not function as a biomarker for rectal cancer." (PMID 25098630, 2014).
intervertebral disc degeneration (5 papers, 2020 to 2025). "Bioinformatics analyses further reveal associations between Adam8 and immune cell populations, including CD8+ T cells and resting memory CD4+ T cells, as well as its involvement in intervertebral disc degeneration." (PMID 41008561, 2025). "Our ongoing work on the role of Adam8 in intervertebral disc degeneration uses a mouse with ADAM8 inactivated by introducing the E330Q mutation into its proteolytic domain." (PMID 32613168, 2020). "As a future therapeutic intervention to retard intervertebral disc degeneration, partial inhibition of ADAM8 proteolysis may be more desirable than complete inactivation of this enzyme." (PMID 33469101, 2021). "The genes that are upregulated in the IVDD group, such as JUNB, SYDE1, ADAM8, and MAFB, are primarily involved in inflammatory responses, extracellular matrix remodeling, and cellular stress responses, which are processes known to be associated with intervertebral disc degeneration." (PMID 39430414, 2024).
allergic asthma (4 papers, 2008 to 2024). A asthma with a basis in a pathological type I hypersensitivity reaction. "Notably, the role of ADAM8 in inflammation has been investigated in multiple diseases of the respiratory system, such as ARDS, allergic asthma, and acute pneumonia, which all showed that ADAM8 promoted leukocyte recruitment, to exacerbate airway inflammation." (PMID 38755530, 2024).
atherosclerosis (4 papers, 2017 to 2025). A disease characterized by the build-up of fatty material and calcium deposition in the arterial wall resulting in partial or complete occlusion of the arterial lumen. "Furthermore, ADAM8 is involved in the development of acute and chronic inflammatory lung diseases, and soluble ADAM8 was shown to be associated with atherosclerosis and myocardial infarction." (PMID 33392273, 2020). "Moreover, this study showed specific ADAM8 polymorphisms (rs2995300C and rs2275725A) to be associated with atherosclerosis development and myocardial infarction in two independent human cohorts." (PMID 28916789, 2017). "Although ADAM10 and ADAM17 have been extensively studied in contexts such as atherosclerosis, the role of ADAM8 in sepsis-induced cardiac dysfunction remains poorly understood." (PMID 41169382, 2025). "While prior studies have shown that ADAM17 can also cleave MerTK in ventilator-induced lung injury and atherosclerosis models, our findings underscore the distinct and context-specific function of ADAM8 in SICM pathogenesis." (PMID 41169382, 2025). "In conclusion, while ADAM8 affects inflammatory responses in vitro, our data argue against a critical role for both hematopoietic and whole-body ADAM8 in atherosclerosis development in female mice, at least in advanced stages of the disease." (PMID 28916789, 2017). "However, it is unclear whether ADAM8 is also causally involved in atherosclerosis development." (PMID 28916789, 2017). "ADAM17 expression was unchanged between ADAM8 wildtype and knockout mice in both atherosclerosis models, suggesting there is no overcompensation for the loss of ADAM8 deficiency although this does not rule out any functional compensation." (PMID 28916789, 2017). "ADAM8 expression has been associated with human atherosclerosis development and myocardial infarction, however a causal role of ADAM8 in atherosclerosis has not been investigated thus far." (PMID 28916789, 2017). "This is the first study that investigated the role of ADAM8 in atherosclerosis development." (PMID 28916789, 2017). "Remarkably, despite the absence of any effects of hematopoietic ADAM8 deficiency on atherosclerosis development, these bone marrow transplanted mice displayed a slight decrease in triglyceride levels at baseline and mild leukopenia both under normo- and hyperlipidemic conditions." (PMID 28916789, 2017). "In addition to the potential dual effects of ADAM8 in atherosclerosis, other ADAMs with a similar substrate profile as ADAM8, such as ADAM1742, might at least partly compensate for the loss of ADAM8." (PMID 28916789, 2017). "Although we show that ADAM8 expression is associated with lesion progression in human disease, genetic ablation of ADAM8 both in the hematopoietic compartment as well as at whole-body level did not affect advanced atherosclerosis development in female mice." (PMID 28916789, 2017). "Therefore, ADAM8 affects processes that inhibit or exacerbate atherosclerosis development, which could explain why we did not observe any change in plaque size or morphology in female ADAM8 deficient mice." (PMID 28916789, 2017). "Note, although no reports on sex specific effects of ADAM8 have been reported, we cannot exclude the possibility that ADAM8 differentially affects atherosclerosis development in males." (PMID 28916789, 2017). "Although, we clearly showed that ADAM8 expression is increased in unstable human atherosclerotic lesion, we did not observe any effects of hematopoietic nor whole-body ADAM8 on advanced atherosclerosis development in mice." (PMID 28916789, 2017).
gastric cancer (4 papers, 2023 to 2025). A primary or metastatic malignant neoplasm involving the stomach. "We calculated population size based on a reference study which evaluated the association between ADAM8 protein and gastric cancer." (PMID 39755747, 2025). "When gastric cancer tissue was paired with normal tissue from the same patient with gastric cancer (n = 32), ADAM8, ADAM9, ADAM10, ADAM12, and ADAM17 mRNAs showed significantly higher expression in gastric cancer tissues (p < 0.05)." (PMID 39755747, 2025). "Gastric cancer tissues (n = 415) expressed significantly higher mRNA levels of ADAM8, ADAM9, ADAM10, ADAM12, and ADAM17 (p < 0.001) than normal tissues (n = 35)." (PMID 39755747, 2025). "As a proof-of-concept pilot study, the expression of ADAM8, ADAM9, ADAM10, ADAM12, ADAM17, and major histocompatibility complex (MHC) class I chain-related sequence A (MICA), a ligand for NKG2D, in gastric cancer was investigated in silico using The Cancer Genome Atlas (TCGA) database." (PMID 39755747, 2025). "The overexpression of ADAM8 was found in some GI cancers such as pancreatic, colon or gastric cancers and was a negative prognostic factor." (PMID 37185715, 2023).
glioma (4 papers, 2019 to 2024). A benign or malignant brain and spinal cord tumor that arises from glial cells (astrocytes, oligodendrocytes, ependymal cells). "Subsequent qPCR validation confirmed a significant increase in mRNA levels of CD30, PRKCQ, and ADAM8 in glioma cell lines (A172, U87MG, and PDX-L14) overexpressing FOSL1, which are key regulators at the apex of the NF-κB signaling pathway." (PMID 38856747, 2024). "In addition, ADAM8 and ADAM19 are correlated with the invasive activity of glioma cells and unfavorable survival, while ADAM9, -10 and -17 are associated with tumor grade and histological type of gliomas and can be used as prognostic factors." (PMID 34638718, 2021). "ADAM8 and ADAM19 are correlated with the invasive activity of glioma cells and may be associated with unfavorable survival, while ADAM9 is associated with tumor grade and histological type in gliomas and might be an independent prognostic factor, especially in LGG patients." (PMID 34638718, 2021). "Additionally, the protease activities and expression levels of ADAM8 and ADAM19 correlated with invasive activity of glioma cells, which suggests that these proteins might play a significant role in tumor invasion and may be associated with unfavorable survival." (PMID 34638718, 2021).
liver cancer (3 papers, 2023 to 2025). An epithelial or non-epithelial malignant neoplasm that arises from the liver. "Adam8 has not been previously linked to the maintenance of the myCAF phenotype in the TMEs of breast or liver cancer." (PMID 37370863, 2023). "The expression of ADAM8 is positively correlated with the activation of MAPK and regulates the proliferation and migration of liver cancer cells." (PMID 39407108, 2024).
metastatic disease (3 papers, 2012 to 2016). "They found that ADAM8 was expressed significantly higher in metastatic tumors as well as identifying several proteinases of the ADAM-family (ADAM9, ADAM17, ADAM28, ADAMTS1, ADAMTS8 and ADAMTS15) -including ADAM8- which are HNSCC associated." (PMID 22369429, 2012).
osteoarthritis (3 papers, 2019 to 2025). A noninflammatory degenerative joint disease occurring chiefly in older persons, characterized by degeneration of the articular cartilage, hypertrophy of bone at the margins and changes in the synovial membrane. "Interestingly, Adam8 demonstrates protective effects in osteoarthritis by inhibiting fibroblast-like synoviocyte migration and invasion through the FSCN1/MAPK pathway." (PMID 41008561, 2025). "Furthermore, ADAM8 was found to cleave fibronectin, contributing to the development of osteoarthritis." (PMID 31640732, 2019).
pancreatic ductal adenocarcinoma (3 papers, 2019 to 2023). An infiltrating adenocarcinoma that arises from the epithelial cells of the pancreas. "U et. al pointed out that ADAM8 regulate the pathway ERK1/2 (extracellular signal–regulated kinases 1/2) signaling to affect the expression of MMPs in pancreatic ductal adenocarcinoma cells." (PMID 31640732, 2019).
pneumonia (3 papers, 2022 to 2024). An acute, acute and chronic, or chronic inflammation focally or diffusely affecting the lung parenchyma, caused by an infection in one or both of the lungs (by bacteria, viruses, fungi, or mycoplasma.). "ADAM8-deficient mice presented with a moderate manifestation of pneumonia, whereas WT control animals developed severe symptoms, as reflected by a higher M-CASS score." (PMID 35132956, 2022). "We then investigated the impact of ADAM8 genetic deletion and pharmacological inhibition in mice with Pseudomonas aeruginosa infection, which is a common pathogen causing severe pneumonia in hospitalized patients and ARDS." (PMID 35132956, 2022). "In mouse pneumonia models, both genetic deletion and pharmacologic inhibition of ADAM8 attenuated neutrophil infiltration and lung injury while improving bacterial containment." (PMID 35132956, 2022). "Consistent with our observation in Adam8–/– mice, the inhibition of ADAM8 reduced the severity of pneumonia." (PMID 35132956, 2022). "Finally, Adam8 metalloproteinase was shown to be responsible for pathological pneumonia-related neutrophil infiltration of the lungs." (PMID 39768135, 2024). "Interestingly, breakdown of a moderately ADAM8-specific FRET substrate correlated with disease severity in BALs of patients with 2 etiologies of ARDS (pneumonia and PGD after lung transplantation)." (PMID 35132956, 2022). "We propose that in acute inflammatory lung diseases such as pneumonia and ARDS, ADAM8 inhibition might allow fine-tuning of neutrophil responses for therapeutic gain." (PMID 35132956, 2022). "To this end, we selected PEPDab013 as the FRET peptide mostly specific for ADAM8, which is based on the ADAM8 cleavage site in CD23 and measured breakdown of this substrate by real-time fluorescence increase in BAL samples of patients with and without ARDS from pneumonia." (PMID 35132956, 2022).
Sepsis (3 papers, 2020 to 2025). Sepsis is defined as life-threatening organ dysfunction caused by a dysregulated host response to infection. "Additionally, ADAM8 or sMer levels may serve as biomarkers to identify sepsis patients at high risk for cardiomyopathy." (PMID 41169382, 2025). "Future directions should include validating this mechanism in human sepsis, developing specific ADAM8 inhibitors, and exploring its interactions with related pathways such as TREM2 signaling." (PMID 41169382, 2025). "In this study, we employed two murine sepsis models to elucidate the pivotal role of macrophage-expressed ADAM8 in SICM." (PMID 41169382, 2025). "Targeting ADAM8 or its downstream effectors may represent a novel therapeutic strategy for sepsis-induced cardiac complications." (PMID 41169382, 2025). "Pharmacological inhibition of ADAM8 could preserve MerTK-mediated efferocytosis, reduce inflammation and apoptosis, and improve cardiac outcomes in sepsis." (PMID 41169382, 2025). "Through in-depth research on the mechanism of ADAM8’s role in SICM, we aim to provide new targets and ideas for the treatment of this disease, ultimately contributing to improving the prognosis of sepsis patients." (PMID 41169382, 2025). "To further corroborate the effect of ADAM8 in macrophages on cardiac function in SICM, we established another sepsis mouse model by CLP." (PMID 41169382, 2025). "Macrophage-specific ADAM8 CKO mice exhibited preserved cardiac function, reduced myocardial injury markers, attenuated apoptosis (decreased Bax/Bcl2 ratio), and enhanced survival in both LPS-induced and CLP sepsis models." (PMID 41169382, 2025).
acute respiratory distress syndrome (2 papers, 2024). Progressive and life-threatening pulmonary distress in the absence of an underlying pulmonary condition, usually following major trauma or surgery. "Previous studies have shown that ADAM8 plays a significant role in neutrophil migration and infiltration, which can help alleviate lung failure associated with acute respiratory distress syndrome." (PMID 38218854, 2024). "Increasing studies have reported that ADAM8 played a vital role in airway inflammation in diseases of the respiratory system, such as acute respiratory distress syndrome (ARDS), asthma, and chronic obstructive pulmonary disease (COPD)." (PMID 38755530, 2024).
brain cancer (2 papers, 2014 to 2024). A primary or metastatic malignant neoplasm affecting the brain. "Previously, ADAM8 expression was correlated with tumor stage or an unfavorable prognosis for patients with esophageal-gastric, lung, pancreatic or brain cancers, and with invasiveness of tumor cells in culture, although little was explored about its mechanism of action." (PMID 24375628, 2014).
chronic myeloid leukemia (2 papers, 2023 to 2024). "Furthermore, ADAM8 has been linked to chemoresistance in solid cancers and tyrosine kinase inhibitor therapy resistance in chronic myeloid leukemia cells." (PMID 39261477, 2024). "ADAM8 is expressed as an antigen of tyrosine kinase inhibitor-resistant chronic myeloid leukemia cells in a model of chronic myeloid leukemia stem cells produced from chronic myeloid leukemia-induced pluripotent stem cells." (PMID 38025763, 2023).
chronic periodontitis (2 papers, 2020 to 2022). A chronic inflammatory process that affects the tissues that surround and support the teeth. "A disintegrin and metalloproteinase 8 (ADAM8), which is localized within the gingival epithelium, exhibits enhanced expression in inflamed tissues affected with chronic periodontitis." (PMID 35478496, 2022). "Moreover, ADAM8 is found significantly elevated in the gingival crevicular fluid of patients with chronic periodontitis and synovia of patients with rheumatoid arthritis." (PMID 35478496, 2022).
degenerative disc disease (2 papers, 2024 to 2025). "ADAM8 proteolytic activities and fibronectin fragments may accelerate degenerative disc disease, a common clinical problem leading to tremendous socioeconomic burdens in the United States." (PMID 39926327, 2025). "ADAM8 is known to cleave fibronectin in IVD tissues, generating pathological fibronectin fragments, which may trigger further disc degeneration." (PMID 39926327, 2025).
eosinophilic pneumonia (2 papers, 2017 to 2024). An inflammatory lung disorder characterized by an increased number of eosinophils in the lungs. "In eosinophilic pneumonia, soluble ADAM8 levels in bronchoalveolar lavage fluid (BALF) and peripheral blood are also found to be notably elevated relative to control groups." (PMID 39588470, 2024). "Soluble ADAM8 levels are significantly elevated in bronchoalveolar lavage fluid in both acute and chronic eosinophilic pneumonia compared to the control group, and a similar increase is observed in peripheral blood of patients with eosinophilic pneumonia." (PMID 39588470, 2024). "Moreover, serum ADAM8 (a disintegrin and a metalloproteinase 8) concentrations were significantly elevated in patients with suspected drug-induced eosinophilic pneumonia induced by suspect drugs." (PMID 28464801, 2017).
inflammatory liver diseases (2 papers, 2021 to 2024). "Studies of ADAM8 and liver disease have also increased recently." (PMID 39407108, 2024).